AFP (alpha fetoprotein)
Diseases named in the same sentence as AFP in open-access papers (continued):
Sharing a sentence is not in itself a finding about the gene and the disease.
tumor (continued). "Tumor antigens and ectopic hormones, such as CEA, AFP, NSE, CA50, CA724, CA125, etc., are currently the most often utilized tumor biomarkers in clinic." (PMID 37400751, 2023). "TLK2 overexpression means a higher level of AFP and ALBI score, worse MVI grade and TNM stage, larger tumor diameter, and greater tumor number in HBV-related HCC patients." (PMID 38343446, 2023). "The clinical data of 374 HCC patients included age, sex, T stage, N stage, M stage, pathologic stage, histologic grade, race, weight, tumor status, OS event, DSS event, PFI event, age, AFP (ng/mL), and prothrombin time." (PMID 37746945, 2023). "The sequential sample collected at the time of tumor resection showed a VAF of 4.8%, while serum AFP levels decreased by approximately threefold between these time points." (PMID 38201440, 2023). "In this paper, we re-evaluate the development of the quality of laboratory testing between 2018 and 2022 for the tumor markers CEA and AFP." (PMID 37370914, 2023). "ctDNA seems to present higher sensitivity compared to the plasma protein biomarkers (such as AFP, CEA and PSA), circulating tumor cells and miRNAs." (PMID 37189699, 2023). "All patients with suspected CCA should be checked for tumor biomarkers (CA 19-9, CEA), and patients with intrahepatic tumors should additionally undergo an AFP check-up." (PMID 36673043, 2023). "In multivariate analysis, AFP (HR: 1.961; 95%CI: 1.140–3.374; P = 0.015), AST/ALT ratio (HR: 2.075; 95%CI: 1.039–4.145; P = 0.039) and tumor numbers (HR: 3.074; 95%CI: 1.832–5.160; P < 0.001) were identified as independent prognostic indicators for OS." (PMID 36944920, 2023). "The modulation of AFP upon TKI therapy is the most frequently used predictive biomarker in HCC patients, together with PD-L1 expression, tumor lymphocyte infiltration and immune class signatures." (PMID 37746265, 2023). "Because high-dose capecitabine had a good antitumor effect, we then compared the expression of AFP and CEA proteins in tumor tissues of the model and high-dose capecitabine groups through western blot assays." (PMID 36742145, 2023). "A univariate analysis showed that AFP, lactate dehydrogenase (LDH), aMAP score, diameter of main tumor, lesion location, number of intrahepatic lesions, and treatment were associated with OS." (PMID 37283795, 2023). "The clinical outcomes of the GC patients are summarized, including CEA, CA19−9, AFP, and HER2 expression, pathologic grade, Union for International Cancer Control (UICC) tumor stage, lymph node involvement, and distant metastases." (PMID 36979667, 2023). "Several tumor markers have been identified for HCC, including alpha-fetoprotein, des-gamma-carboxy prothrombin, and glypican-3." (PMID 38093163, 2023). "For a second multivariate COX analysis, we chose pT-category, tumor to liver SUV ratio and pre-transplant AFP-level." (PMID 35451699, 2023). "After the seventh course, the serum levels of AFP and DCP were within the normal range, the intrahepatic HCC had shrunk to 70 mm with regression of the hilum tumor contact, and the patient was diagnosed with a partial response to the modified RECIST." (PMID 37266831, 2023). "Another study found that tumor markers such as CEA, CA19-9 and AFP were prognostic factors for GC and that H. pylori infection is most common cause of GC." (PMID 37828556, 2023). "In atezo/bev therapy, focusing on early AFP changes, baseline DCP, and tumor burden of up-to-seven criteria are useful in predicting response to treatment." (PMID 37296889, 2023). "Routine blood test, liver and kidney function, and tumor markers like cancer antigen 125 (CA125), cancer antigen 199 (CA199), carcinoembryonic antigen(CEA), alpha-fetoprotein (AFP) were normal." (PMID 37328769, 2023). "Integrated evaluation of tumor markers and CT features, including tumor location, PCA, and serum AFP, allowed for more accurate differentiation of GHA from GA." (PMID 37538113, 2023).
tumor (continued). "Emerging evidence shows that AFP is not only a biomarker for diagnosis but also participates in the progression of HCC by regulating proliferation, apoptosis, and autophagy of tumor cells and the inhibition of immune cell function." (PMID 36755690, 2023). "In fact, only a few patients showed AFP‐positivity by immunohistochemistry, probably because AFPGC cells constitute only a small fraction of the entire tumor tissue." (PMID 37017469, 2023). "Tumours in both groups displayed well‐differentiated ductular morphology, high CK19 expression and low levels of AFP." (PMID 35924447, 2023). "And DFS in HCC patients was affected by the levels of TRIP13 protein, tumor size, number of tumors, TNM stage, and AFP levels (50 g/L versus > 50 g/L) (P < 0.05)." (PMID 37740123, 2023). "In atezo/bev therapy for unresectable HCC, the change in AFP levels at 3 weeks in patients with baseline AFP level ≥ 20 ng/mL and baseline DCP level or tumor burden in those with AFP level < 20 ng/mL were found to predict treatment response." (PMID 37296889, 2023). "Some serum tumor markers, such as carbohydrate antigen (CA199), carcinoembryonic antigen (CEA), carbohydrate antigen (CA125), alpha‐fetoprotein (AFP), and prostate‐specific antigen (PSA) have been widely used to diagnose and screen cancer." (PMID 35879835, 2023). "The combination of AFP and serum EV-SF3B4 exhibited an AUC of 0.942 (95% CI:0.908–0.966) in the HCC vs. non-tumor model and an AUC of 0.935 (95% CI:0.899–0.962) in the HCC vs. CH/LC model." (PMID 37899451, 2023). "Tumor micronecrosis can improve the predictive efficiency of Milan criteria, MELD score, and AFP level." (PMID 36698095, 2023). "The factors included tumor size, tumor number, TBIL, AST, ALT, PLT, CRE, Child-Pugh score, albumin-bilirubin (ALBI) grade, Up-to-7 criteria, AFP, PIVKA-II, and the proposed methylation indexes." (PMID 37760434, 2023). "Our analysis showed that TRIP13 protein levels were significantly correlated with the individual’s alpha-fetoprotein (AFP) level, tumor number, and incomplete encapsulation (all P < 0.05)." (PMID 37740123, 2023). "The value of tumour markers, total beta-human chorionic gonadotropin and lactate dehydrogenase (LDH) were <2.39 mIU/ml and 417 U/l respectively and alpha-fetoprotein (AFP): 500 ng/ml." (PMID 37203966, 2023). "It was found that the expression levels of AFP and CEA in tumor tissues of the model group were higher than those of the treatment groups." (PMID 36742145, 2023). "Alpha-fetoprotein (AFP) and carbohydrate antigen 19-9 (CA 19-9) are established circulating tumour markers related with HCC and CCA, respectively." (PMID 36612297, 2023). "The AFP and CEA are considered significant tumor biomarkers that have been reported to be increased in HCC-bearing rats." (PMID 37266135, 2023). "The FAIL-T score comprised five routine parameters in HCC patients, including the largest tumor size, the number of tumors, and liver function tests such as serum AST and ALT levels, and AFP level." (PMID 37200967, 2023). "TIMER analysis showed that DNAJB1, COL10A1, PTGS2, AFP, and EGF were correlated with tumor-infiltrating lymphocytes." (PMID 36967783, 2023). "For example, Zou and co-workers proposed a spectrum-resolved triplex-color ECL multiplexing immunoassay for the simultaneous determination of three different tumor markers, CEA, PSA and AFP." (PMID 37504107, 2023). "In crude cohort and sIPTW cohort, univariate analysis showed that the prognostic factors affecting OS were tumor number, PVTT type, treatment modality, and alpha-fetoprotein (AFP) (P < 0.05)." (PMID 36920551, 2023). "There were significant differences in tumor size (p < 0.001), presence of MVI (p < 0.001), AFP level (p = 0.006), AST level (p = 0.005), GGT level (p = 0.007), and peritumoral stiffness (p = 0.020) between the recurrence group and non-recurrence group." (PMID 37697029, 2023).
tumor (continued). "It found that AFP and a Charlson comorbidity score were the most predictive preoperative factors for BCLC-0 and A patients, and radiologic tumor burden score proved to be the most predictive for BCLC-B patients." (PMID 37296890, 2023). "In particular, patients after chemotherapy with vital residual tumours have more grade III–V complications, whereas a preoperatively increased AFP is an independent parameter." (PMID 37490059, 2023). "Alpha-fetoprotein (AFP) and carbohydrate antigen 19-9 (CA 19-9) are blood tumour markers related with HCC and CCA, respectively." (PMID 36612297, 2023). "Firstly, univariate analysis in the training cohort showed that gender, AFP, DCP, BCLC stage, tumor number, tumor size, globulin, DBIL, albumin-to-prealbumin ratio (APR), and fibrinogen (Fib) were significantly associated with RFS." (PMID 36936655, 2023). "The patient’s tumor marker levels, including soluble interleukin-2 receptor (IL-2R), carcinoembryonic antigen (CEA), alpha-fetoprotein (AFP), and human chorionic gonadotropin (HCG), were within the normal ranges." (PMID 39516947, 2023). "Tumor markers such as alpha-fetoprotein and abnormal prothrombin are effective indicators to judge the prognosis of HCC, but many patients have normal tumor markers when they are diagnosed with HCC." (PMID 37519805, 2023). "For patients with HCC and MVI, maximum tumor diameter, poor cell differentiation, and APPRI were independent predictors for DFS and poor cell differentiation, APRI, APPRI, PT, and AFP were independent prognostic factors for OS." (PMID 37492981, 2023). "Currently, serum biomarkers, such as alpha-fetoprotein (AFP), human chorionic gonadotropin (HCG), and lactate dehydrogenase (LDH), and the Tumor Node Metastasis (TNM) classification were used to assist to make treatment decisions for TGCT patients." (PMID 36882567, 2023). "By univariate and multivariate Cox regression analysis, we confirmed previous studies indicating serum AFP levels ≥ 400 ng/ml and detection of EpCAM-positive CTC in peripheral blood prior to tumor resection as prognostic markers." (PMID 38012205, 2023). "In the OS analysis, GGT, DB, AFP, PNI, NLR, SIRI, MVI, tumour diameter, and PVTT were selected using LASSO regression analysis." (PMID 35255845, 2022). "The response of alpha-fetoprotein (AFP), another HCC tumor marker, 6 weeks after initiating Atz/Bev therapy, has been reported to be a potential surrogate biomarker for prognosis in patients with HCC." (PMID 36551574, 2022). "Post-TACE tumor fraction assessed the remaining tumor burden and was detectable in 81.3% of HCC patients compared to AFP that was detected in 70.3%." (PMID 36230569, 2022). "Serum indicators AFP, CA50, CA125, CA153, CA19-9, CEA, f-PSA, SCC-Ag have been confirmed as tumor markers (TMs)." (PMID 35144566, 2022). "In addition, the prognostic characteristics constructed in this study might predict the different prognostic outcomes of two TCGA groups stratified by tumor grade (G1+G2 or G3+G4), sex (male or female), AFP content (< 20 or ≥ 20 ng/ml), age (> 60), T stage (T1+T2) and clinical stage (I + II)." (PMID 36267406, 2022). "Other authors reported that alpha-fetoprotein (AFP)-expressing, DC-derived exosomes possess anti-tumor activity mediated by the activation of IFN-γ-expressing CD8+ T cells with a simultaneous decrease in Tregs." (PMID 36551798, 2022). "The expression profiles of genes in the first cluster across all tumours (TOP2A, CDK1, BIRC5, GPC3, IGF2 and AFP) were strongly correlated." (PMID 36345011, 2022). "There were no major associations between cfDNA concentration/integrity and gender, age, TNM stage, tumor location, NSE, and AFP expression within the patients' pre/postchemotherapy CRC cohort, all at P > 0.05." (PMID 35685424, 2022). "The variables selected included age, gender, alanine transaminase level, ALBI grade, prothrombin time, AFP level, CSS, tumor number, tumor size, and macrovascular invasion and vascular invasion." (PMID 35637856, 2022).
tumor (continued). "Reassuringly, we found a decrease in AFP and OPN and an increase in HMGA1 and Hep-Par1 staining in Myc-R26Met versus Alb-R26Met tumours." (PMID 36433941, 2022). "To address these issues, we studied the dynamics of tumor-specific T cells induced by ablative therapy during a specific follow-up period post-ablation using SALL4, MAGE-A1, MAGE-A3, NY-ESO-1, SSX2 and AFP to stimulate the antitumor T cell response." (PMID 36618423, 2022). "Specifically, neutrophil-lymphocyte ratio ≤5, alpha-fetoprotein (AFP) > 200 ng/ml and tumor size >3 cm have been classified as pre-transplantation predictive factors of decreased recurrence-free survival." (PMID 35859667, 2022). "Testicular tumor markers such as beta-HCG, alpha-fetoprotein (AFP), and lactate dehydrogenase (LDH) were in the normal range." (PMID 35337334, 2022). "As is known to all, AFP, CEA, CA199, CA153, CA125, and CA50 are common tumor markers of the digestive system." (PMID 35710379, 2022). "Before PSM, univariate analysis showed that PVTT invasion, tumor number, treatment (TACE-A or TACE-AP), AFP, and total bilirubin (TBIL) level were the prognostic factors affecting OS (P < 0.05)." (PMID 36249011, 2022). "Univariable and multivariable analysis revealed that, in addition to MVI grade and treatment allocation, tumor size, tumor number, PLT, AFP, and interval of recurrence from initial treatment were also independent prognostic factors." (PMID 35814378, 2022). "Furthermore, validation of our coculture experiments using AFP specific TCR-T cells showed that knockdown of LAGE3 in HepG2 cells could increase the sensibility of tumor cell death induced by cytotoxic T cells and the ability of cytokine secretion of cytotoxic T cells." (PMID 35433409, 2022). "In agreement with effective tumor suppression, significantly larger numbers of T cells specific for the GSMLNEHVM AFP peptide were detected in DEXP&A2&N-treated mice than DEXP&A2 and PBS controls." (PMID 35488312, 2022). "Sex, age, degree of differentiation, AFP, ALB, HBV, HCV, Child-Pugh score, tumor number, surgical method, MVI, postoperative treatment, postoperative surgery, postoperative TACE or HAIC and postoperative drugs were included as predictors in the PSM." (PMID 35928871, 2022). "In contrast, many studies have found that α-fetoprotein (AFP) and protein induced by vitamin K absence or antagonist-II (PIVKA-II), which are tumor markers for HCC, predict postoperative prognosis." (PMID 36358711, 2022). "In the analysis of the single-detection results of tumour markers, CEA had the highest sensitivity (23.94%), CA153 had the highest specificity (96.43%), AFP had the highest accuracy (47.66%) and CA153 had the highest area under the curve (AUC) value (0.727)." (PMID 36755860, 2022). "Through logistic regression analyses, we confirmed that the age, Child–Pugh class, ALBI grade, AFP, ALP, platelet, ALT, leukocyte, tumor diameter, and PVTT were independent influencing factors for the HSP90α expression." (PMID 35972640, 2022). "In a word, the characteristics including rim enhancement, tumor capsule, TTPVI, and AST in AFP-NHCC patients should receive adequate attention." (PMID 35626229, 2022). "Regarding quantitative data, patients with a high Ki-67 expression had higher alpha-fetoprotein (AFP) levels, larger tumor size, higher T1rt-pre, higher T1rt-20min, and lower ADC (all P < 0.05)." (PMID 36313692, 2022). "EXO1 expression levels showed a significant correlation with the race, AFP levels, DSS, OS, T stages, tumor status, histologic grades, and pathologic stages of the HCC patients." (PMID 35769911, 2022). "We discovered that HuoxueHuayu therapy had an obvious advantage in reducing CEA and AFP, but the tumor markers CEA and AFP can be found in various cancers instead of unique cancer, so they lack tumor specificty." (PMID 38094221, 2022).
tumor (continued). "TACE was preferred to curative approaches in older patients, in those with ECOG-PS≥1, CRPH, higher MELD (except for LT specifically), and greater tumor burden (in terms of number and size of nodules, MVI, EHS, and high AFP levels)." (PMID 35174092, 2022). "Studies have shown that common tumour markers, such as CEA, alpha fetoprotein (AFP), carbohydrate antigen 125 (CA125), carbohydrate antigen 199 (CA199) and carbohydrate antigen 153 (CA153), can make up for the deficiency in imaging to some extent." (PMID 36755860, 2022). "The predictive ability of the established nomogram (Model 3) was superior to that of Model 1 (TNM staging system), Model 2 (TNM staging system + AFP + CEA), and Model 4 (tumor size + NLR + PLR + OPNI)." (PMID 35277188, 2022). "Univariate analysis showed that age (P < 0.001), tumor site (P = 0.005), TNM stage (P < 0.001), MLR (P = 0.006), ALI (P = 0.018), SII (P < 0.001), CA19-9 (P = 0.019), and AFP (P = 0.014) were statistical prognostic factors." (PMID 35296020, 2022). "It is possible that AFP is secreted more as the tumor proliferates, as VEGFR2 expression is positively correlated with tumor size." (PMID 36313714, 2022). "Tumor markers beta‐human chorionic gonadotropin (BHCG), lactate dehydrogenase (LDH), and alpha‐fetoprotein (AFP) were normal." (PMID 35251647, 2022). "In that study, hsa_circ_0003570 was also associated with several clinicopathological characteristics, such as tumor size, tumor differentiation, microvascular invasion, BCLC stage, TNM stage, and AFP level." (PMID 36011395, 2022). "Univariate Cox regression analysis revealed that the PPP1R26 expression level, tumor number, microscopic vascular invasion, Edmondson-Steiner grade, BCLC stage and AFP level were the significant prognostic indicators in HCC (P < 0.05, respectively)." (PMID 35292107, 2022). "All serologic tumor markers to include carcinoembryonic antigen (CEA), carbohydrate antigen (CA) 19-9, alpha fetoprotein (AFP), beta-human chorionic gonadotropin (HCG), prostate-specific antigen (PSA), and lactate dehydrogenase (LDH) were normal." (PMID 36203172, 2022). "The hepatic expression of STAT5 in our HCC patients was found to be inversely correlated with the tumor size, vascular invasion, TNM tumor stage, and serum level of AFP." (PMID 36374927, 2022). "Biomarkers such as alpha‐fetoprotein (AFP), cell‐free DNA (cfDNA), and circulating tumour cells (CTC) are used in humans to help predict and identify HCC recurrence." (PMID 35488436, 2022). "Total tumor volume (TTV), AFP, etc., have been reported as predictors for successful downstaging from outside the Milan criteria to within the Milan criteria." (PMID 35053558, 2022). "In the TCGA cohort, 245 patients with complete information including age, gender, tumor grade, TNM stage, vascular invasion and alpha-fetoprotein (AFP) were included for multivariate Cox regression analysis." (PMID 36685838, 2022). "One of the most widespread and attractive tumor-targeting ligands is alpha-fetoprotein (AFP) and its analogs, which are able to be internalized specifically by a range of tumor cells and tissues." (PMID 35328540, 2022). "Tumor markers (HCG and AFP) are examined in blood serum and cerebrospinal fluid (CSF) from lumbar puncture or ventricular drainage when it is safe to obtain the sample for the latter." (PMID 36132131, 2022). "In the 2-year RFS analysis, ALT, ALBI, AFP, PNI, APRI, MVI, number of tumour, tumour diameter, tumour capsule, and PVTT were selected." (PMID 35255845, 2022). "Moreover, its expression level was associated with HCC clinicopathological characteristics, such as tumor size, differentiation, lymph node metastasis, microvascular invasion, and the serum AFP level, suggesting that circ_0003570 might be a helpful prognostic biomarker of HCC." (PMID 36241975, 2022).